IGKV1-27 (immunoglobulin kappa variable 1-27)
Description:
V region of the variable domain of immunoglobulin light chains that participates in the antigen recognition. Immunoglobulins, also known as antibodies, are membrane-bound or secreted glycoproteins produced by B lymphocytes. In the recognition phase of humoral immunity, the membrane-bound immunoglobulins serve as receptors which, upon binding of a specific antigen, trigger the clonal expansion and differentiation of B lymphocytes into immunoglobulins-secreting plasma cells. Secreted immunoglobulins mediate the effector phase of humoral immunity, which results in the elimination of bound antigens. The antigen binding site is formed by the variable domain of one heavy chain, together with that of its associated light chain. Thus, each immunoglobulin has two antigen binding sites with remarkable affinity for a particular antigen. The variable domains are assembled by a process called V-(D)-J rearrangement and can then be subjected to somatic hypermutations which, after exposure to antigen and selection, allow affinity maturation for a particular antigen.
Synonyms: IGKV127; A20
Gene: Immunoglobulin variable (V) gene on chromosome 2 (89,213,423 to 89,213,928, reverse strand). Ensembl gene ENSG00000244575.
Subcellular location: Secreted; Cell membrane
Gene Ontology:
Biological process: immune response
Cellular component: extracellular region; immunoglobulin complex; plasma membrane
Homologues: Orthologues: chimpanzee IGKV1-27 (85% identical). Paralogues in human: IGKV1-9 (91% identical), IGKV1-12 (90% identical), IGKV1-16 (89% identical), IGKV1-39 (89% identical), IGKV1D-12 (89% identical), IGKV1D-39 (89% identical), IGKV1D-13 (88% identical), IGKV1D-16 (88% identical), IGKV1-17 (87% identical), IGKV1-37 (87% identical), IGKV1-6 (87% identical), IGKV1D-37 (87% identical), and 81 more.
Diseases named in the same sentence as IGKV1-27 in open-access papers:
IGKV1-27 is named in the same sentence as 1 disease in open-access papers, as found by Europe PMC text mining. Sharing a sentence is not in itself a finding about the gene and the disease.
IGKV1-27 shares sentences with these, for which no sentence is quoted: thymoma (1 paper).